CD4 (CD4 molecule)
Diseases named in the same sentence as CD4 in open-access papers (continued):
Sharing a sentence is not in itself a finding about the gene and the disease.
Arthritis (continued). "Moreover, CD4+T cells isolated from arthritic joints and splenocytes express IL-22 after the induction of AIA, suggesting the possible involvement of IL-22 in this model of arthritis." (PMID 26330334, 2015). "Thus, CD4+ T cells are not required for arthritis progression once the disease clinically manifests in the CIA model." (PMID 26290328, 2015). "Our results indicate that CD4+ T cells are not required for disease progression once arthritis is established, because the mice treated with only GK1.5 showed comparable disease progression or a trend towards more severe disease progression compared with the control groups." (PMID 26290328, 2015). "Either A12-immune or control CD4+ T cells were infused intravenously into DR1 tg mice prior to immunization with bCII/CFA, so that mice could be observed for effects on collagen-induced arthritis." (PMID 24405551, 2014). "However, a relationship between inverted CD4+/CD8+ ratio and arthritis is presently unclear." (PMID 24885015, 2014). "Accordingly, it has been reported that depletion of specific collagen-reactive T cells ameliorated collagen-induced arthritis without systemic immunosuppression and, importantly, osteoclastogenesis was inhibited by apoptotic induction of activated CD4+ T cells using anti-Fas mAb." (PMID 23308194, 2013). "As a consequence, the tissue is endowed with local changes that are likely to prevent the onset of arthritis directly within the local environment where inflammation would occur, even following a later exposure to curdlan at a time (day 60) where anti-CD4 MAbs are no longer present." (PMID 20479941, 2010). "However, it should be noted, that some anti-CD4 treated mice developed mild manifestations of arthritis following curdlan challenge at day 60, although without progressing to the severe manifestations of the disease observed in control groups." (PMID 20479941, 2010). "Animals exposed to curdlan in the presence of the putative tolerogenic anti-CD4 MAb at day 0 were protected from the induction of arthritis following curdlan administration at day 60, unlike the age-matched controls that did not receive any treatment at day 0 (n = 6, P<0.05)." (PMID 20479941, 2010). "The observation that administration of anti-CD4 mAb after the onset of arthritis did not ameliorate the arthritis and a combination of mAb to CII can passively transfer arthritis to naïve mice also emphasises the importance of autoantibodies to the induction of collagen-induced arthritis." (PMID 18992137, 2008). "Surprisingly, 1 × 106 pre-activated CD4+CD25+ cells had no influence on either knee joint swelling or histological arthritis score when transferred at day 1 or day 7 after induction of arthritis." (PMID 15743476, 2005). "However, Bardos and coworkers ruled out a role for naturally occurring CD4+CD25+ Treg cells in proteoglycan-induced arthritis." (PMID 15743476, 2005). "Thus, the failure in arthritis development following transfer of CD4+ T cells into Csf2−/− hosts could be attributed not to impaired Th17 cell differentiation but to impaired GM-CSF production by certain host non-T cells stimulated by Th17 cells." (PMID 29802020, 2018). "Finally, sham-operated and thymectomized mice subjected to antibody treatment and subsequent immunization appeared equally protected from CIA, compared with nondepleted mice, excluding a role for recent B22a1+CD4+ thymic emigrants in the later-occurring arthritis (data not shown)." (PMID 20682070, 2010). "Moreover, CD4+ T cells, especially Th17 cells, seem to be more important than B cells, because administration of anti-CD4 mAb or anti-IL-17 mAb markedly ameliorate the progress of arthritis independent of anti-GPI antibodies titres." (PMID 18992137, 2008). "Notably, in proteoglycan-induced arthritis, another model of autoimmune arthritis, it has been shown that CD4+CD25+ Treg cells might not have a critical role." (PMID 15743488, 2005).
Arthritis (continued). "In contrast, SKG.luc+CD4+ T cell bioluminescence signal increased transiently in the spleen of BALB/c mice at day 7 and did not progress to joint recruitment or arthritis." (PMID 40762957, 2025). "No increased uptake in tissues with mild arthritis and healthy tissue was observed, indicating specific targeting of our CD4 PET tracer, [64Cu]Cu-NOTA-CD4, in lesions with mild inflammation." (PMID 36114433, 2022). "Flow cytometry analysis showed significantly increased recruitment of CD45+CD4+Ccr6+ (Th17) cells and CD45+CD4–Ccr6+ (expected as a B cell–rich fraction) cells in arthritis tissue from Uhrf1ΔCol6a1 mice in the late but not early phase of STA." (PMID 35472067, 2022). "Although arthritis severity was not exacerbated by HS diet compared to RS diet in our CIA studies, IL-17A expression was analyzed in splenic CD4+-T cells of CIA mice by flow cytometric analysis." (PMID 34925335, 2021). "In the absence of Egr2/3, PD-1high MP CD4 T cells are highly inflammatory but have impaired homeostasis and T-cell function, a phenotype discovered recently in SLE and arthritis." (PMID 32709717, 2020). "In this context, CD4+CCR6+ T cells, but not γδ T cells, are crucial for the progressive phase of arthritis." (PMID 31778214, 2020). "During early arthritis, IL‐23R(GFP)+CD4+CCR6+ T cells, but not IL‐23R(GFP)+ γδ T cells, were present in the inflamed joints." (PMID 31778214, 2020). "Unexpectedly, dko KRN.g7 mice also had levels of differentiated autoreactive CD4+ T cells that were indistinguishable from wt KRN.g7 mice, despite their reduced arthritis and autoantibody production." (PMID 32973768, 2020). "CD4+CD62L- and CD8+CD62L- cell proportions of AOSD were not changed after improvement, even though AOSD also showed arthritis." (PMID 31614573, 2019). "While our data suggest that CREM directly regulates CD4+CD161+ T cells in human JIA, we cannot fully transfer this observation to our in vivo arthritis model as the murine analog of CD161 has not yet been identified." (PMID 29925386, 2018). "Supporting their potential role in the pathogenesis of arthritis, at 20 weeks the number of spleen Tregs, but not total CD3+CD4+ T cells, inversely correlated with the inflammation score (r=−0.65, P<0.03, Pearson's correlation)." (PMID 25963626, 2015). "We identified 18 CD8+ T cell clones (4 patients: 2 flare, 2 DFR), four CD4+ T cell clones (4 patients: 2 flare, 2 DFR), and no B cell clones which showed a significant change in circulating proportional abundance at onset of arthritis flare." (PMID 38316770, 2024). "In contrast, when classes have samples from multiple sources, this does little to decrease the importance of the source concept, as can be observed in the arthritis TCAV scores where monocyte and CD4+ concepts have high TCAV scores, as opposed to the PBMC score which is low in this class." (PMID 38468193, 2024). "Finally, adoptive transfer experiments revealed that CD4+CCR6+ T cells and not γδ T cells drive arthritis progression." (PMID 31778214, 2020). "Furthermore, CD4+CCR6+ T cells, but not γδ T cells, are important for IL‐23R‐dependent progression of arthritis." (PMID 31778214, 2020). "Remarkably, infiltrating CD4+ but not CD8+ T cells were found in the injured synovial tissue of these chronic CHIKV patients, suggesting a role of these lymphocytes in the chronic arthralgia/arthritis." (PMID 31276466, 2019). "In BD patients with arthritis in our data, the frequencies of CCR7-CD62L-CD4+, CCR7-CD62L-CD8+ effector memory T cells, and CCR7+CD62L+CD4+, CCR7+CD62L+CD8+ central memory T cells were not different compared to HC or RA in PBL whole cells and in lymphocytes populations." (PMID 31614573, 2019). "Furthermore, IL-17 is no less important in the pathogenesis of arthritis and is produced by Th17 cells (CD3+, CD4+) and found in inflamed synovia." (PMID 30059520, 2018).
Arthritis (continued). "Next to regulation of CD4+ IL-17+IFN-γ- T cells by IL-23, data from the present study also show marked reduction of CD4+ IL-17+IFN-γ+ double positive cells in the absence of IL-23 during arthritis." (PMID 20017902, 2009). "To determine whether the beneficial effects in S. aureus arthritis were due to Tregs or other IL2-mediated effects, we adoptively transferred CD4+CD25+ Tregs and found a clear, although not statistically significant, tendency to a reduction of both the clinical arthritis and bone erosion." (PMID 32111171, 2020). "Interestingly, following either CD4+ or CD8+ T cell depletion, neutrophil numbers in joints of WT control mice were significantly increased, although this did not result in an increase in arthritis severity." (PMID 27857714, 2016). "Similarly, adoptive cell transfer of CD4+CD25+ T cells from spleens and lymph nodes into immunized mice at the time of induction of CIA decreased the severity of disease but was not able to cure established arthritis." (PMID 20384988, 2010).
colorectal cancer (335 papers, 2003 to 2026). A primary or metastatic malignant neoplasm that affects the colon or rectum. "Integrating Mendelian randomization and colocalisation, we identify CD4+ T cell subtype- and activation-specific gene expression changes that causally influence colorectal cancer risk, revealing dynamic relationships and potential preventive targets." (PMID 40974097, 2025). "Based on the IVW method, Activated & resting Treg %CD4 + cells show a positive correlation with risk of colorectal cancer, while DN (CD4-CD8-) %leukocyte cells is suggested to have a protective effect against CRC." (PMID 38902711, 2024). "Survival analysis of immune cell levels in colorectal cancer showed that higher levels of immune cells, such as CD4+ T cells or macrophages, were associated with worse overall survival." (PMID 38577591, 2024). "Plasma cells and CD4+ T cells have been linked to the prognosis of colorectal cancer, as evidenced by previous studies." (PMID 39684481, 2024). "A recent study demonstrated that FAM110B was an immune-related hub gene in colorectal cancer and its expression was positively associated with the infiltration of multiple immune cells, such as CD4 T cells, macrophages, neutrophils, and dendritic cells." (PMID 37310469, 2023). "The abundance of activated CD4 memory T cells has been reported to be associated with patient prognosis in multiple solid tumors, such as colorectal cancer, small-cell lung cancer, and hepatocellular carcinoma." (PMID 36330451, 2022). "We previously showed that vaccination with RNA-LPX encoding for CD4+T cell neoantigens augments cellular responses generated by LRT via in situ release of tumor antigens in a mouse tumor model of colorectal carcinoma, CT26." (PMID 34971406, 2022). "In murine colorectal cancer model, forced expression of β-catenin in CD4+ T cells caused increased IL-17A expression that favor tumor progression." (PMID 32132993, 2020). "Increasing infiltration of CD4+ T lymphocytes at tumor margins has been proven to be associated with less recurrence and better prognosis in colorectal cancer and HCC." (PMID 25505815, 2014). "In summary, the results of the present study show that, in patients undergoing curative resection for colorectal cancer, low tumour CD4+ T-lymphocyte infiltration is associated with elevated C-reactive protein concentrations." (PMID 15700032, 2005). "We determined that microsatellite stable (MSS) colorectal cancers had an increased risk of recurrence if they had the following features: 1) a low level of stromal tumor-infiltrating lymphocytes, and 2) low interactions between CD4 + T cells and stromal cells." (PMID 40189697, 2025). "The CD4+/CD8+ T cell ratio is associated with colorectal cancer prognosis." (PMID 39605357, 2024). "CD4+ T cells consist of various subsets, and a previous study showed that higher Th1 subset and lower Th17 subset are associated with favorable prognosis in colorectal cancer." (PMID 36621808, 2023). "In addition, such a gene has been shown to be associated with exhausted CD4 T cell activation during the progression of colorectal cancer." (PMID 37763280, 2023). "Indeed, a low CD4+/CD8+ T-cell ratio and CD4+ T-cell presence in the blood was linked with a favorable anti-PD-1 IO outcome for MMR-deficient colorectal carcinomas." (PMID 37232754, 2023). "However, in some cancers, including colorectal cancer, a high number of tumor‐infiltrating CD4+FOXP3+ T cells was shown to be associated with improved survival." (PMID 32377339, 2020). "Thus, an increase in circulating PD‐1+ CD4+ T cells (and in myeloid-derived suppressor cells) following RT completion was, for example, associated with reduced T cell activity in colorectal cancer patients." (PMID 32519025, 2020). "Similarly, a previous study of patients with colorectal cancer showed that Tregs suppressed effector CD4+ T cell responses to tumor-associated antigen before tumor resection, and the suppression was associated with tumor recurrence." (PMID 30824840, 2019).
colorectal cancer (continued). "Indeed, increased infiltration of the tumour by CD8+ and CD4+ T-lymphocytes has been shown to be associated with increased survival in patients with colorectal cancer." (PMID 15700032, 2005). "In the present study, a poor tumour CD4+ T-lymphocyte infiltrate was associated with an elevated circulating C-reactive protein concentration in patients undergoing potentially curative resection for colorectal cancer." (PMID 15700032, 2005). "Indeed, ICOS/CD4 correlation has been reported in colorectal cancer, where expression is associated with improved survival and may be a clinical biomarker for good prognosis." (PMID 32487090, 2020). "In a murine study, DEX showed inhibition of colorectal cancer growth by modulation of CD4+ and CD8+ T cells." (PMID 41409241, 2025). "For example, SNHG4 was expressed highly in colorectal cancer, and promotes apoptosis of CD4+ T cells through a miRNA sponge binding to miR-144-3p and competing with the MET oncogene." (PMID 41154428, 2025). "The immune cell ratio box plot suggests that there are significant differences in naive B cells, memory B cells, plasma cells, activated CD4 memory T cells, activated NK cells, resting NK cells, etc., between colorectal cancer tumor tissue and normal tissue." (PMID 40868987, 2025). "According to the immune cell infiltration heatmap, resting CD4 memory T cells, plasma cells, naive B cells, M0 macrophages, and M2 macrophages showed the highest immune infiltration in all samples of TCGA colorectal cancer." (PMID 40868987, 2025). "A monoclonal antibody targeting CSF-1R depleted TAMs and increased the CD8+/CD4+ T cell ratio, leading to decreased primary tumor burden and decreased metastasis in mouse models of colorectal cancer and fibrosarcoma." (PMID 40646332, 2025). "Although our analysis focused on CD3+ and CD8+ T-cell infiltration, CD4+ T-cell involvement represents an additional layer of immune regulation in colorectal cancer." (PMID 41462871, 2025). "For instance, elevated levels of CD8+ T cells have been associated with improved disease-free survival in various cancers, including colorectal cancer, where a high presence of both CD4+ and CD8+ T cells correlates with better overall prognosis (p<0.05)." (PMID 41583321, 2025). "Our results indicate that there are significant differences in naive B cells, memory B cells, plasma cells, activated CD4 memory T cells, activated NK cells, resting NK cells, etc., between colorectal cancer tumor tissue and normal tissue." (PMID 40868987, 2025). "A putative role of the CDK4/6 signaling and the cyclin inhibitor p21 in the immune status of colorectal cancer and the anti-tumor fitness of infiltrating CD4+ T cells was proposed in a study of colorectal cancer in mice." (PMID 40699853, 2025). "Another study traced CD4+ T-cell clones in colorectal cancer via paired scRNA/TCR-seq from tumors, adjacent normal tissue, and blood samples from 12 patients." (PMID 40634636, 2025). "Validation with a cohort of 23 colorectal cancer (CRC) samples confirms the significant impact of TGF-β1+ CD4+ and CXCL13+ CD4+ and CD8+ T cells on ICB efficacy." (PMID 40054456, 2025). "In particular, CD4+ Tregs within the PerIS are increased in individuals with peritoneal metastasized colorectal cancer." (PMID 39044825, 2024). "The results indicated that both Activated & resting CD4 regulatory T cell %CD4 T cell (Treg panel) and DN (CD4-CD8-) T cell % leukocyte (TBNK panel) demonstrated significant causal associations with colorectal cancer across various research cohorts." (PMID 38902711, 2024). "In colorectal cancer liver metastasis, the emergence of CD4+FOXP3+ Tregs, coupled with elevated levels of α-smooth muscle Actin, HGF, and c-MET, suggests potential therapeutic targets for this metastatic variant of colorectal cancer." (PMID 39664377, 2024).